RNU6-206P (RNA, U6 small nuclear 206, pseudogene)
Gene: Small nuclear RNA gene on chromosome 7 (139,315,291 to 139,315,394, reverse strand). Ensembl gene ENSG00000206843.
Homologues: Orthologues: chimpanzee U6 (97% identical), guinea pig U6 (77% identical), rat LOC120100172 (71% identical). Paralogues in human: RNU6-116P (88% identical), RNU6-140P (87% identical), RNU6-16P (87% identical), RNU6-33P (87% identical), RNU6-480P (87% identical), RNU6-1 (86% identical), RNU6-1038P (86% identical), RNU6-1251P (86% identical), RNU6-2 (86% identical), RNU6-39P (86% identical), RNU6-3P (86% identical), RNU6-46P (86% identical), and 1287 more.